L1CAM (L1 cell adhesion molecule)
Diseases named in the same sentence as L1CAM in open-access papers (continued):
Sharing a sentence is not in itself a finding about the gene and the disease.
gastric cancer (continued). "We therefore analyzed the relationship between expression of EPCAM/L1CAM and prognosis of patients with gastric cancer according to regional lymph nodes." (PMID 24422715, 2013). "The current study examined expression of L1CAM and EPCAM in surgical specimens of gastric carcinoma, to explore possible correlations between L1CAM and EPCAM expression and clinicopathological variables and prognosis." (PMID 24422715, 2013). "In the present study, we found L1cam is overexpressed in gastric cancer cells and tissues." (PMID 23806079, 2013). "Western blot analysis confirmed overexpression of L1cam in all gastric cancer cell lines." (PMID 23806079, 2013). "However, further study is needed to investigate the interaction of L1cam and integrins in gastric cancer cells." (PMID 23806079, 2013). "In this study, we found L1cam was overexpressed in gastric cancer tissues and cell lines." (PMID 23806079, 2013). "L1cam was overexpressed in gastric cancer tissues and cell lines." (PMID 23806079, 2013). "Consistent with decreased MMP-9 levels, C-PAC and AFG decreased expression of L1CAM in JHAD1 cells, a neuronal adhesion protein linked to metastasis and chemoresistance, and is overexpressed in many solid tumor cancers including esophageal squamous cell carcinoma and gastric cancer." (PMID 35267943, 2022). "Targeting L1cam might be a promising therapeutic strategy for gastric cancer patients." (PMID 23806079, 2013). "To avoid biasing the prognostic value of EPCAM/L1CAM by tumor stage, we analyzed the relationship between expression of EPCAM/L1CAM and prognosis of patients with gastric cancer according to TNM stage." (PMID 24422715, 2013). "The present study investigated the clinical significance of L1CAM and EPCAM in the development, progression and prognosis of gastric cancer." (PMID 24422715, 2013). "Expression of L1CAM and EPCAM were examined immunochemically in 601 clinicopathologically characterized gastric cancer cases." (PMID 24422715, 2013). "Overexpression of L1cam promotes cell proliferation, migration and invasion, chemoresistanse as well as tumorigenesis and metastasis via activation of PI3K/Akt signaling pathway in gastric cancer." (PMID 23806079, 2013). "The study revealed that depth of invasion (P=0.007), lymph node (P = 0.009) and distant metastasis (P = 0.01), TNM stage (P = 0.008), expression of L1CAM (P = 0.007), and of EPCAM (P = 0.009) were independent prognostic factors in patients with gastric carcinoma." (PMID 24422715, 2013).
Alzheimer disease (15 papers, 2014 to 2025). A progressive, neurodegenerative disease characterized by loss of function and death of nerve cells in several areas of the brain leading to loss of cognitive function such as memory and language. "We reported at the beginning of the COVID-19 pandemic that neuronal-enriched or L1CAM+ extracellular vesicles (nEVs) from people with LongC contained proteins associated with Alzheimer’s disease (AD)." (PMID 38612641, 2024). "NCAM1 and L1CAM have been implicated in cell adhesion, neurite outgrowth, and synaptic plasticity, which are processes that are disrupted in Alzheimer's disease." (PMID 38502590, 2024). "Proteomic analysis of immunoprecipitated ATP1A3+ brain-derived EVs reveals a greater enrichment of synapticmarkers and Alzheimer-disease-related cargo proteins than that ofNCAM1+ or L1CAM+ EVs." (PMID 40720603, 2025). "Increased levels of L1CAM might therefore be beneficial for older orthopedic patients, and this is similar to the idea that exogenous expression of L1CAM is beneficial in Alzheimer's disease." (PMID 32194463, 2020).
lymph node metastasis (15 papers, 2016 to 2026). "In summary, the positivity rate of L1CAM in BC CTCs, particularly the high positivity rate in H-CTCs, was closely associated with aggressive tumor features such as lymph node metastasis and elevated Ki-67 index." (PMID 41306535, 2025). "Specifically, L1CAM+ H-CTCs are significantly associated with lymph node metastasis, while L1CAM+ M-CTCs correlate with PR status, suggesting their potential involvement in tumor micrometastasis and hormone receptor-related pathways." (PMID 41306535, 2025). "This study aimed to clarify the clinical and biological significance of CTCs in early-stage invasive breast cancer (ESIBC) by investigating the association between CTC phenotypic heterogeneity, L1CAM expression, and lymph node metastasis." (PMID 41306535, 2025). "A higher H-CTC count was associated with an increased probability of lymph node metastasis, and positive L1CAM expression also markedly elevated the risk." (PMID 41306535, 2025). "Analysis of clinical data showed that the levels of L1CAM were significantly associated with lymph node metastasis in GC (P<0.05)." (PMID 32742486, 2020). "Apart from the direct prognostic implications of L1CAM in cancer patients, L1CAM expression was positively associated with tumour progression, lymph node metastasis and the risk of loco regional or distant recurrence in most included cancer types." (PMID 27833079, 2016). "In our evaluation, none of the traditional risk factors including the multifactor risk assessment for the presence of lymph-nodes metastasis was superior to methylation of L1CAM promotor." (PMID 27233077, 2016). "Given the frequent association of L1CAM with lymph node metastasis, one could wonder if preoperative L1CAM expression can predict lymph node metastasis and prevent unnecessary morbidity of lymph node excision." (PMID 40870967, 2025). "Taken together, these findings indicate that elevated H-CTC counts, positive L1CAM expression, and high Ki-67 levels may serve as potential risk factors for lymph node metastasis in BC patients." (PMID 41306535, 2025). "L1CAM levels in the blood were also associated with lymph node metastasis and poor outcome." (PMID 40870967, 2025). "Moreover, high expression of L1CAM correlated significantly with the occurrence of lymph node metastases, both in the whole patient population and in the low-risk subgroup." (PMID 32429448, 2020). "Hybrid CTCs (H-CTCs) and L1CAM-positive CTCs were significantly correlated with lymph node metastasis and Ki-67 expression." (PMID 41306535, 2025). "L1CAM positivity was detected in 71.6% of peripheral blood CTCs, primarily localized to H-CTCs, and served as an independent predictor of lymph node metastasis (OR ≈ 8.37)." (PMID 41306535, 2025). "ROC analysis further indicates that the combination of H-CTCs, L1CAM+ M-CTCs, and Ki-67 markedly improves the accuracy of predicting lymph node metastasis." (PMID 41306535, 2025). "The combined detection of H-CTCs and L1CAM enhances preoperative prediction of lymph node metastasis and provides new insights into BC metastasis mechanisms." (PMID 41306535, 2025). "Factors traditionally associated with a high risk of recurrent disease include histologic subtype, FIGO G3 histology, myometrial invasion ≥50%, LVSI,25, 26, 27 L1 cell adhesion molecule expression, lymph node metastases and tumour diameter >2 cm." (PMID 36696825, 2023). "Tumours with high L1CAM expression had more lymph node metastasis (P = 0.003) and distant metastasis (P = 0.007) than those with low L1CAM expression." (PMID 31754264, 2019).
lymph node metastasis (continued). "In addition, the Mann Whitney U test revealed that L1CAM positivity was significantly correlated with sentinel lymph node metastasis (p = 0.011)." (PMID 36142656, 2022). "A high negative predictive value of L1CAM for lymph node metastasis in a non-high-risk-patients cohort would allow for consideration of de-escalating surgical procedures." (PMID 34659530, 2021). "When considering the entire cohort or the risk groups, L1CAM was not a predictor for lymph node metastasis." (PMID 34659530, 2021). "The levels of L1CAM in GC were significantly associated with lymph node metastasis (P<0.05), but not with other clinical data, including age, gender, smoking, depth of invasion, metastasis and TNM stage." (PMID 32742486, 2020). "However, stratification by lymph node metastasis revealed a significant difference: patients with lymph node metastasis had a mean L1CAM+ T-CTC count of 5.05 ± 6.987, which was significantly higher than that of patients without metastasis (2.58 ± 4.849, p = 0.048)." (PMID 41306535, 2025). "However, to date, no study has shown that L1CAM can be used for preoperative prediction of risk for recurrence, lymph node metastasis and distant metastasis." (PMID 31754264, 2019). "L1CAM expression was correlated with clinicopathological features such as histological subtype, FIGO stage, lymph node metastasis, lymphadenectomy, adjuvant treatment and outcome." (PMID 34659530, 2021). "L1CAM is not a reliable predictor for lymph node metastases, and therefore preoperative L1CAM assessment is not recommended." (PMID 34659530, 2021). "Out of these patients without lymph node metastasis, 66 (75%) were L1CAM negative and 22 (25%) L1CAM positive." (PMID 34659530, 2021). "As for the relationship between serum L1CAM and the clinical data of GC and EJA, we found that the level of serum L1CAM was associated to lymph node metastasis (P<0.05) in GC but there was no statistical difference with EJA." (PMID 32742486, 2020). "Patients with L1CAM positive tumours were more likely to have lymph node metastasis than patients without L1CAM expression (48.3% vs 35.4%, P=.048)." (PMID 27028855, 2016). "Patients with L1CAM positive tumours presented more often at the highest FIGO stage (31.1% vs 6.9%, P=.023) and if they had lymph node metastasis, it was more likely to be bilateral (31.3% vs 8.0%, P=.029) and with extracapsular growth (37.5% vs 12.6%, P=.024)." (PMID 27028855, 2016). "L1CAM expression strongly correlates with non-endometrioid histology, LVSI and lymph node metastasis." (PMID 35530346, 2022).
non-small cell lung carcinoma (15 papers, 2011 to 2025). A group of at least three distinct histological types of lung cancer, including non-small cell squamous cell carcinoma, adenocarcinoma, and large cell carcinoma. "In a study comprising 438 non-small cell lung cancer (NSCLC) patient tissues, neuroserpin and adhesion protein L1CAM expression signified correlation with pathological features but did not impinge on the overall survival rates." (PMID 35244780, 2022). "Currently, no data of L1CAM are available for non-small cell lung cancer (NSCLC)." (PMID 21985405, 2011).
pancreatic adenocarcinoma (11 papers, 2013 to 2025). "In addition, an increase of invasiveness in 5‐FU resistant pancreatic adenocarcinoma cell lines was functionally linked to L1CAM expression." (PMID 34228897, 2022). "It has been reported that the expression of L1CAM in pancreatic adenocarcinoma cells resulted in constitutive activation of NFkB,30 and L1CAM‐mediated signalling has been linked to NFkB activation." (PMID 40289262, 2025). "In fact, accumulating evidence suggests that L1CAM can induce constitutive NF-κB activation in pancreatic adenocarcinoma cells." (PMID 35473609, 2022). "It has been reported that Integrin α5 was indispensable for L1CAM mediated chemo-resistance in pancreatic adenocarcinoma cells." (PMID 35517416, 2022). "Our findings establish Slug-induced L1CAM expression as a mediator of a chemoresistant and migratory phenotype in pancreatic adenocarcinoma cells." (PMID 25860483, 2015). "Finally, protein kinase C-alpha (PKCα) phosphorylates the Thr1172 residue within the L1CAM cytoplasmic domain, thus regulating important properties of pancreatic adenocarcinoma cells such as motility." (PMID 32429448, 2020).
ependymoma (10 papers, 2018 to 2024). A WHO grade II, slow growing tumor of children and young adults, usually located intraventricularly. "Ependymomas with ZFTA::RELA fusion reveal cytoplasmic positivity for L1CAM and diffuse nuclear staining for p65 protein (encoded by RELA gene)." (PMID 38544524, 2024). "Immunohistochemistry should be performed for EMA or podoplanin, GFAP, BCOR, and p65-RELA or L1CAM for ZFTA-RELA ependymomas." (PMID 36604386, 2023). "The latest WHO guideline of CNS tumor defined a RELA fusion-positive ependymoma type with extremely poor prognosis, and the expression of L1CAM was correlated well with the presence of RELA fusion." (PMID 32509846, 2020). "It is well known that high expression of L1CAM correlates well with the presence of RELA fusion in supratentorial ependymomas." (PMID 32509846, 2020). "Expression of L1CAM correlated well with the presence of a RELA fusion in supratentorial ependymomas." (PMID 32509846, 2020). "Together with our results, L1CAM expression may be more related to C11orf95 than to RELA in ST ependymomas and ELTMDs with fusion genes involving C11orf95." (PMID 33576087, 2021). "Immunohistochemistry studies distinguished supratentorial ependymomas in the RELA-fusion-positive and the yes-associated protein 1 (YAP1)-fusion positive subgroups, the Neural cell adhesion molecule L1 (L1CAM) protein marking the first one and showing the most aggressive behavior." (PMID 32183175, 2020). "The ST-EPN-RELA subgroup can be identified by immunostaining for the surrogate markers L1 cell adhesion molecule (L1CAM) or anti-NFkB (p65, RelA), the latter based on the discovery that C11orf95–RELA fusions drive oncogenic NF-kB signalling in ependymoma." (PMID 29098416, 2018). "In addition, L1CAM, which was originally identified as a neural adhesion molecule essential for axonogenesis, was reported to be overexpressed in ST ependymomas with C11orf95‐RELA, suggesting that L1CAM is a target of aberrant signaling of the fusion proteins." (PMID 33576087, 2021). "Neural cell adhesion molecule L1 (L1CAM), one of the protein products of the RELA fusion gene, is of interest, and Nambirajan and Witt reported that programmed death ligand-1 (PD-L1) is upregulated in ST-RELA ependymomas." (PMID 33387039, 2021). "It was worth noting that expression of L1CAM correlated well with the presence of a RELA fusion in supratentorial ependymomas, and this new type presented in 2016 WHO blue book of CNS tumors had the worst outcome in ependymomas." (PMID 32509846, 2020). "Differently from ZFTA-fused ependymomas, they are negative for both L1CAM and p65." (PMID 38544524, 2024). "However, supratentorial ependymoma is characterized by clear cell morphology, negativity for oligodendrocyte transcription factor 2 (OLIG2), dot-like epithelial membrane antigen (EMA) positivity, and positivity for L1 cell adhesion molecule (L1CAM) and p65/RELA markers." (PMID 39440342, 2024). "In ST ependymomas with YAP1‐MAMLD1, another molecular subgroup of ST ependymoma, no positivity for L1CAM was observed in any of the 11 cases tested." (PMID 33576087, 2021). "Interestingly, several RELAFUS target genes such as L1CAM and IGF2 were not necessarily common in 293T and mouse ependymoma cells in our analyses, indicating the fact that the transcriptional programs activated by RELAFUS are context-dependent." (PMID 33685520, 2021).
pancreatic ductal adenocarcinoma (10 papers, 2013 to 2025). An infiltrating adenocarcinoma that arises from the epithelial cells of the pancreas. "Positive L1CAM expression in pancreatic ductal adenocarcinoma was associated with node involvement, vascular invasion, perineural invasion, higher degree of pain, and poor survival." (PMID 24422715, 2013). "TGF-β1 was previously shown to reduce L1CAM expression in a model of pancreatic ductal adenocarcinoma, paralleling our findings." (PMID 40307935, 2025). "It was also reported that L1CAM expression is correlated with perineural invasion and poor outcomes in pancreatic ductal adenocarcinoma." (PMID 35008571, 2021). "Although the mechanism by which L1CAM promotes proliferation and cell invasion in pancreatic ductal adenocarcinoma remains to be determined, studies have investigated the role of L1CAM-dependent activation in the MAPK-ERK signaling pathway." (PMID 24660028, 2014). "L1CAM staining was unrelated to tumor phenotype in muscle-invasive urothelial carcinoma, clear cell and papillary RCC, serous high-grade carcinoma of the ovary, endometrioid endometrium carcinoma, gastric adenocarcinoma and in pancreatic ductal adenocarcinoma." (PMID 41328908, 2025).
serous ovarian cancer (9 papers, 2016 to 2025). "Yet, current insight into L1CAM-mediated carcinogenesis and radioresistance, particularly in the most common and lethal type of OC, high-grade serous ovarian carcinoma (HGSOC), remains limited." (PMID 40429728, 2025). "The glycoprotein L1 cell adhesion molecule (L1CAM) is overexpressed in high-grade serous ovarian carcinoma (HGSOC) and plays a crucial role in carcinogenesis by regulating cancer stem cell properties." (PMID 40429728, 2025). "Finaly, Altevogt and collaborators measured the levels of both membrane and soluble L1CAM in a cohort of high grade serous ovarian cancer patients." (PMID 32429448, 2020). "(A) Quantification of NOVA2- and L1CAM-positive vessels in healthy ovaries (n = 5) and high-grade serous ovarian cancer (OC) (n = 5)." (PMID 30829570, 2019). "There was a significant difference in L1CAM expression according to various histological subtypes, with the highest expression in serous ovarian cancer and the lowest in mucinous tumors (p=0.003)." (PMID 27174921, 2016). "After all, the miR-34a regulated L1CAM expression contributes to the invasive and metastatic phenotype of serous ovarian carcinoma." (PMID 26879132, 2016). "This first phosphoproteomics study of L1CAM knockout in high-grade serous ovarian carcinoma cells links L1CAM-dependent tumorigenesis and radioresistance, both hallmarks of cancer stemness, with phosphorylation of key proteins involved in DNA repair and mTORC1 signaling." (PMID 40429728, 2025). "Furthermore, the L1CAM expression was analyzed using a quantitative ELISA in ascitic fluid of serous ovarian carcinoma." (PMID 27174921, 2016).
Spastic paraplegia (9 papers, 2016 to 2024). Complete loss of the ability to move the lower limbs accompanied by spasticity of the lower limbs. "Among the patients with ALS2, SACS, and L1CAM variants in our cohort, several exhibited clinical symptoms characteristic of spastic paraplegia." (PMID 37251230, 2023). "Mutations in L1CAM are also associated with MASA syndrome (characterized by mental retardation, aphasia, shuffling gait, and adducted thumb), and spastic paraplegia, highlighting the pleiotropic role of L1CAM in human disease." (PMID 38439105, 2024). "L1CAM is a pathogenic gene that, when mutated, causes various disorders including MASA syndrome (mental retardation, aphasia, shuffling gait, and adducted thumbs), X-linked hydrocephalus, spastic paraplegia, and corpus callosum agenesis." (PMID 37943774, 2023).